RNU6-523P (RNA, U6 small nuclear 523, pseudogene)
Gene: Small nuclear RNA gene on chromosome 10 (67,858,818 to 67,858,871, reverse strand). Ensembl gene ENSG00000252113.
Homologues: Orthologues: chimpanzee U6 (100% identical), rabbit U6 (87% identical), rat LOC120103237 (83% identical), pig U6 (81% identical), mouse Gm24965 (80% identical), guinea pig U6 (74% identical). Paralogues in human: RNU6-338P (96% identical), RNU6-653P (96% identical), RNU6-116P (94% identical), RNU6-187P (94% identical), RNU6-658P (94% identical), RNU6-1060P (93% identical), RNU6-1151P (93% identical), RNU6-1243P (93% identical), RNU6-1248P (93% identical), RNU6-1251P (93% identical), RNU6-24P (93% identical), RNU6-298P (93% identical), and 1283 more.